FGA (fibrinogen alpha chain)
Diseases named in the same sentence as FGA in open-access papers (continued):
Sharing a sentence is not in itself a finding about the gene and the disease.
osteosarcoma (1 paper, 2023). A usually aggressive malignant bone-forming mesenchymal neoplasm, predominantly affecting adolescents and young adults. "Among the DEPs identifying oseoblastic and telangiectatic osteosarcoma subtypes are CAT, FGA, SLC4A1, and ACTA2." (PMID 37681913, 2023).
ovarian serous carcinoma (1 paper, 2013). "Nonetheless, Q-RT-PCR analysis corroborated elevated F2, FGA and FGB transcript levels in a small, independent set of freshly-frozen ovarian CCC (n = 6) compared to ovarian serous carcinomas (n = 7) (P≤0.01, Mann-Whitney U-test)." (PMID 24040285, 2013).
pemphigus vulgaris (1 paper, 2024). Pemphigus is a group of chronic autoimmune skin diseases characterized by blister formations on the outer layer of the skin and the mucous membranes. "The dysregulation of genes such as FGA, VWF, and ACTG1 suggests that alterations in their transcription and expression may contribute to the pathogenesis of pemphigus vulgaris." (PMID 39593117, 2024). "Among these genes, FGA, VWF, and ACTG1 were abnormally expressed, supporting the hypothesis that platelet activation may play an important role in the progression of pemphigus vulgaris." (PMID 39593117, 2024).
periodontitis (1 paper, 2024). An acute or chronic inflammatory process that affects the tissues that surround and support the teeth. "Interestingly, we found that FGA, a gene that plays an important role in periodontitis, was substantially elevated during aging." (PMID 38577810, 2024).
preeclampsia (1 paper, 2022). Preeclampsia is a hypertensive disorder of pregnancy that is characterized by new-onset hypertension with proteinuria presenting after 20 weeks of gestation, and depending on mild or severe forms may initially present with severe headache, visual disturbances, and hyperreflexia. "The up-regulation of FGA is believed to contribute to the pathogenesis of preeclampsia by participating in the trophoblast recast of uterine spiral artery, activation of systemic inflammatory response and injury of endothelial cells." (PMID 36304541, 2022).
primary open-angle glaucoma (1 paper, 2024). "In agreement with our results, the downregulation of FGA (fibrinogen alpha chain), FGG (fibrinogen gamma chain), and HBB (hemoglobin subunit beta) was assessed in primary open-angle glaucoma patients’ aqueous humor." (PMID 39000104, 2024).
psychosis (1 paper, 2024). "C4B, Complement C4-A (C4A), Complement C2 (C2), A2M, LRG1, and the Fibrinogen alpha, beta, and gamma chains (FGA, FGB, and FGG) were differentially expressed between those who transitioned to psychosis and those who did not, adjusting for age, sex, and study." (PMID 38243809, 2024).
schizophrenia (1 paper, 2017). A major psychotic disorder characterized by abnormalities in the perception or expression of reality. "We sought further to demonstrate that variants in the fibrinogen alpha chain gene (FGA) coded FPA might confer vulnerability to schizophrenia." (PMID 28203040, 2017). "Thus, the explanation of the association between FGA variants and schizophrenia was rational." (PMID 28203040, 2017). "At present, our study did not observe a significant association of FGA polymorphisms and schizophrenia." (PMID 28203040, 2017). "Our findings suggested that FGA polymorphisms might not be associated with the susceptibility to schizophrenia." (PMID 28203040, 2017).
squamous cell carcinoma (1 paper, 2024). A carcinoma arising from squamous epithelial cells. "In this work, our screening uncovered previously unidentified prognostic gene expression indicators, namely, MYO1E, FAM83 homologs, and DKK1 for adenocarcinoma, and FGA and TRIB1 for squamous cell carcinoma." (PMID 39513892, 2024).
systemic amyloidosis (1 paper, 2022). "Mutation of FGA can result in hereditary systemic amyloidosis." (PMID 35463955, 2022).
ZIKV infections (1 paper, 2021). "FGA and other fibrinogens are components of blood clots and involved in early wound repair; and perturbation in coagulation has been linked to both Zika and dengue infections." (PMID 33582300, 2021). "Further, we used a machine learning approach to distinguish between the DENV and ZIKV infections based on protein expression profiles of the 13 differentially proteins and a subset of three proteins (FGA, PF4V1, PPBP)." (PMID 33582300, 2021).
tumor (30 papers, 2015 to 2026). "Following clinical confirmation in the serum, we found that increased expression of these proteins, especially TPR and FGA, was associated with acquired resistance and tumor recurrence." (PMID 40722683, 2025). "Specifically, in certain tumor types, high FGA expression was associated with poorer OS and DSS, indicating its potential role as a negative prognostic marker." (PMID 39130639, 2024). "Emerging evidence has demonstrated that FGA functions as a tumor suppressor, whose genetic mutations could promote hepatocarcinogenesis through disruption of its tumor-suppressive regulatory mechanisms." (PMID 40861466, 2025). "Our in-vivo xenograft studies demonstrated that FGA knockdown significantly accelerated tumor growth in immunodeficient mice, suggesting FGA suppresses LUAD progression." (PMID 40861466, 2025). "In previous studies, FGA has been found to have an effect on tumor metastasis, although its expression levels varied among different cancers." (PMID 39227068, 2024). "We detected the significant downregulation of the expression of genes encoding acute phase proteins (e.g., FBG, FGA, and FGG) and tumor-associated genes such as SERPINC1 and F2." (PMID 38203636, 2023). "Among them were genes associated with blood clotting (FGA, FGG) and genes associated with changes in the immune characteristics of a tumor (ENAM, IGFBP1, IL6)." (PMID 36028558, 2022). "Here, our study showed a tumor suppressor role of FGA in LUAD." (PMID 40861466, 2025). "For instance, FGA may function as an inhibitory factor, presenting itself as a potential target for clinical interventions and tumor treatments." (PMID 38779081, 2024). "In addition, acute phase proteins (ORM1, CRP, SAA1) and complement cascade components (SERPINA1, C5, FGA) showed an obviously significant correlation with tumor size, reflecting a positive connection between inflammatory response and tumor size." (PMID 37460463, 2023). "In addition to tumor progression, FGA was also reported to be the acute phase protein with differential expression in response to injury and inflammation." (PMID 32530819, 2020). "Meanwhile, the elevated levels of TSP-1 and FGA in ESCC patients might synergistically contribute to tumor progression and metastasis." (PMID 26993605, 2016). "In contrast, GLYs, such as the fibrinogen family (FGA, FGB, and FGG), fibronectin (FN1), transforming growth factor beta-induced protein (TGFβI), and tenascin-C (TNC), had an increased presence in tumor tissues." (PMID 40032993, 2025). "In this study, our findings provide evidence that FGA plays a role in immune cell infiltration and the formation of immunotherapeutic responses in LUAD, while also identifying its tumor-suppressive role." (PMID 40861466, 2025). "These analyses provide insights into how CNV and methylation variations influence the expression of FGA and NOTCH3 across various cancer types, potentially contributing to differential tumor behavior and aiding in identifying new therapeutic targets." (PMID 39130639, 2024). "Through bioinformatics analysis and agarose gel electrophoresis, we found that FGA was downregulated in HCC and correlated with tumor stage and grade." (PMID 39227068, 2024). "In contrast, when FGA was knocked out, the expression both increased, indicating that FGA knockout activated the PI3K/AKT signaling pathway, promoting tumor metastasis." (PMID 39227068, 2024). "Of note, seventeen of thirty-nine proteins are reported as urine biomarkers in different diseases, of which eight proteins (PEBP1, EPS8L2, SERPINA1, FGA, SPINT1, CD55, SPARC, and GINM1) are related to neoplastic disease in urine specimens." (PMID 36918772, 2023). "This study established a seven-gene profile (FGG, C3, FGA, JUN, CST3, CPSF4, and HIST1H2BH) prognostic stratification system demonstrated in LUSC based on Tumor Progression, Immune Infiltration, and Stem Index." (PMID 37841237, 2023).
tumor (continued). "The results showed that the expression of FGA, OTC, and CTH in the tumor tissues of patients with CCA is significantly lower than that in normal tissues, but that the expression of MMP11 is significantly higher than that in normal tissues." (PMID 36300097, 2022). "Within the tumor microenvironment (TME), where myeloid and T cells demonstrate preferential glucose uptake over malignant cells, the secreted protein FGA orchestrates tumor matrix remodeling and immune response modulation through xCT expression regulation, thereby shaping clinical prognosis." (PMID 40861466, 2025). "Additionally, among downregulated hub genes, the expression of acyl-CoA oxidase 1 (ACOX1), apolipoprotein A2 (APOA2), apolipoprotein B (APOB), fibrinogen alpha chain (FGA), and fibrinogen gamma chain (FGG) were negatively correlated with the tumor stage of CCA patients." (PMID 35326644, 2022). "The expressions of APOB, FGA, FGG, APOA1, and F2 were significantly down-regulated in the TCGA-LIHC cohort (P<0.05), but SERPINC1 levels were not significantly different between normal and tumor tissues (P>0.05)." (PMID 33834191, 2021).
cancer (25 papers, 2008 to 2025). A tumor composed of atypical neoplastic, often pleomorphic cells that invade other tissues. "Building on these findings, FGA mRNA levels were shown to be modestly higher in HCC patients compared to non-cancer controls, reflecting its potential as a biomarker for distinguishing between these groups." (PMID 40506936, 2025). "When performing pairwise comparisons among the different stages of cancer, stage IV patients had increased expression of FGA, FGB, PERP, GPR107, CDH3 compared to controls." (PMID 39146279, 2024). "Fibrinogen is a protein that is encoded by three different genes (FGA, FGB, FGG), two of which were upregulated in plasma samples from cancer patients in the current study." (PMID 39146279, 2024). "Amongst them, the fibrinogen alpha chain (FGA) was found to be consistently upregulated in the proteomic analysis and the cancer cohort of the patient sample analysis." (PMID 36832201, 2023). "DIA-MS analysis on independent cohort validated the results, showing that phosphorylation level of FGA in EV was significantly high in the serum of cancer patients." (PMID 36293212, 2022). "Fibrinogen, another important member of the coagulation cascade, undergoes altered expression in different types of cancer, and it has been reported that the expression of FGA is increased in serum from ALL patients." (PMID 31437251, 2019). "In previous studies, STR loci AR, BAT-25, D5S346, ER1, ER2, and FGA were reported to be closely related to the occurrence of malignant carcinomas." (PMID 31179189, 2019). "Initially, on the basis of several previous studies, we focused on six different STR loci, including AR, BAT-25, D5S346, ER1, ER2, and FGA, which were reported to be closely related to the occurrence of malignant carcinomas." (PMID 31179189, 2019). "Similarly, emerging evidence implicates dysregulation and decreased expression of RhoGAPs (ARHGAP1), B4GAT1, and FGA in various malignancies, including cancer." (PMID 39819313, 2025). "Additionally, FGA, a component of fibrinogen, plays a role in the extracellular matrix (ECM) and is involved in remodeling processes associated with both exercise and cancer." (PMID 39130639, 2024). "The high serum level of FGA in cancer patients may be due to the release of pro-coagulant factors from endothelial cells and platelets, the latter of which were stimulated by cancer cells." (PMID 29719494, 2018). "This newfound stability has enabled the identification of specific mRNA markers, such as Fibrinogen Chain A (FGA) mRNA, which has been shown to significantly differentiate HCC from non-cancer controls in plasma cfRNA profiling studies." (PMID 40506936, 2025). "Further differential expression analysis of FGA and NOTCH3 across these cancers highlighted significant gene expression differences, with overall changes shown in a bar plot and specific changes depicted in a dot plot." (PMID 39130639, 2024). "Other genes down-regulated by rosiglitazone belonged mainly to two functional groups: “cancer” (RPS27A, SORBS2, STIP1, FGA, FGFR2, SSH3, EPN1) and cell death (SORBS2, STIP1, GAS2, EPN1)." (PMID 22761953, 2012). "Extracellular vesicle (EV) derived proteomic, in combination with phosphoproteomic of serum of CRC patients, preliminarily identified four proteins (FGA, FN1, S100A9, HP), with the phosphorylated forms significantly upregulated in samples from cancer patients compared to healthy individuals." (PMID 36293212, 2022). "The five proteins that met our criteria for an increase in relative abundance in the cancer compared to the control were haptoglobin (HAPT), orosomucoid-1 (ORM1), leucine-rich alpha-2-glycoprotein-1 (LRG1), alpha-1 antichymotrypsin (AACT), and fibrinogen-alpha (FGA)." (PMID 20546617, 2010). "Significant negative correlations were observed between FGA expression and overall survival (OS), disease-specific survival (DSS), and progression-free interval (PFI), with cancer-specific correlations illustrated." (PMID 39130639, 2024).
infection (12 papers, 2012 to 2025). The state of being infected such as from the introduction of a foreign agent such as serum, vaccine, antigenic substance or organism. "The results of research showed that the FGA gene is expressed in the liver tissue of Salmo salar after infection by A. salmonicida, which demonstrating that the FGA may play an important role in the innate immune response to bacterial invasion in Atlantic salmon." (PMID 36360229, 2022). "As FGA/NA d1d and FGA/NA a5c differ by only three amino-acid substitutions in the E protein, we will investigate further the modulation of the Ube2l6 protein and its interaction with the replication complex during infection with the recombinant viruses generated in this study." (PMID 22530074, 2012). "On the other hand, 24 genes were significantly upregulated by infection in the R line of the HSF flock, such as CD19, CD22, CD79B, two complement-related genes CFI and CR2 (complement C3d receptor 2), FGG, and FGA (fibrinogen alpha chain)." (PMID 30678719, 2019). "Increase in genes associated with intrinsic and common coagulation pathways, namely KNG1 and FGA, are upregulated early in both HTNV and ANDV infection (6 hpi to 2 dpi) and peak expression occurs coinciding with ANDV viremia (FGA >11 log2 fold on 10 and 12 dpi, KNG1 >4 log2 fold on 10 and 12 dpi)." (PMID 34339406, 2021).
myopathies (2 papers, 2015 to 2026). "Birds suffering from this myopathy exhibit down-regulation of eight hemostatic genes (A2M, FGA, FGB, FGG, KNG1, SERPINC1 and VWF) and up-regulation of four other coagulation genes (F5, F10, PROS1 and F2R)." (PMID 26445145, 2015). "Fibronectin 1, fibrinogen alpha chain, musculoskeletal embryonic nuclear protein 1, glutathione S-transferase 2, calsequestrin-2, and endoplasmin emerged as potential biological markers and their prospective roles in the pathogenesis of these myopathies are discussed." (PMID 42278140, 2026).
kidney disease (1 paper, 2019). "Among the three cases of unilateral PKD discovered in this study, P45’s case may have been caused by an HNF1B mutation, while P46 and P47 had no gene mutations on the kidney disease panel and P47 had LYZ, FGA, and GLI3 heterozygous mutations on the WES." (PMID 31056860, 2019).
lung (1 paper, 2025). "In this study, we detected A1AG1 and FGA in the tissues and sera of patients with lung ADC receiving a combination of cisplatin and gemcitabine." (PMID 39940778, 2025). "Collectively, these findings suggest that FGA can be classified as a tissue-specific serum protein and may serve as a blood-based biomarker for predicting the response of patients with lung ADC to treatment with platinum and antimetabolite drugs." (PMID 39940778, 2025).
FGA also shares sentences with these, for which no sentence is quoted: acute lymphocytic leukemia (2 papers); esophageal squamous cell carcinoma (2); hypercoagulable (2); melanoma (2); migraine (2); non-small cell lung carcinoma (2); Obesity (2); thromboembolic disease (2); acute coronary syndrome (1); adenocarcinoma (1); age (1); Alzheimer disease (1); Arterial thrombosis (1); autoimmune disease (1); Barrett esophagus (1); bile duct carcinoma (1); biliary tract cancer (1); bladder cancer (1); blood disorder (1); Calcium oxalate nephrolithiasis (1); cardiovascular disease (1); cervical cancer (1); Chronic renal failure (1); colitis (1); colon adenocarcinoma (1); colon cancer (1); complication (1); Crohn disease (1); dementia (1); developmental delay (1).
A further 45 diseases each share a sentence with FGA in 1 paper.